IL6 (interleukin 6)
Diseases named in the same sentence as IL6 in open-access papers (continued):
Sharing a sentence is not in itself a finding about the gene and the disease.
Obesity (continued). "In case of patients with comorbidities (obesity, diabetes, hypertension) or dysregulated immunity, the treatment regimen could further include antiinflammatory drugs (e.g., anti-IL6/anti-IL6R) and RAS inhibitors and hrACE2 for the diabetic patients, in particular." (PMID 33402434, 2021). "Previous studies showed that insulin resistance/hyperinsulinemia, abnormal endogenous estrogen signaling, inflammatory cytokines, and adipocytokines (IL-6, TNF-α, adiponectin, visfatin, and leptin) may be the main mechanisms behind obesity that is associated with EC." (PMID 34975754, 2021). "In addition, indicators of metabolic dysfunction and more severe asthma were also characteristics of non-obese IL-6-high asthmatics, indicating that IL-6 is associated with metabolic dysfunction and severe asthma, even in the absence of obesity." (PMID 33418879, 2021). "Obesity is accompanied by low-grade inflammation characterized by increased pro-inflammatory cytokines and adipokines, and release of interleukin-1β (IL-1β), interleukin-6 (IL-6), TNF-α, and leptin by white adipose tissue (WAT) cells or inflammatory cells infiltrating obese adipose tissue." (PMID 33673390, 2021). "Chronic inflammation involves obesity and elevates insulin resistance, which gives rise to an abnormal production adipocytokines such as leptin, tumor necrosis factor α, prothrombotic mediator plasminogen activator inhibitor-1 (Pal-1), interleukin-1, and interleukin-6." (PMID 35223819, 2021). "Severity of obesity resulted to be associated with lower plasma levels of oxytocin (p = 0.053), vitamin D deficiency (p = 0.006) and higher plasma levels of IFN-γ (p = 0.004), IL-6 (p = 0.013), IL-7 (p = 0.013), TNF-alpha (p = 0.036) and chemokine ligand 3 (CCL3) (p = 0.013, R2 = 0.03)." (PMID 33809270, 2021). "Another interesting study showed that leptin and IL-6 induce anorexia by acting on the lateral parabrachial nucleus (lPBN) in the brain, suggesting that targeting leptin might be controlling the IL-6 signaling in individuals with obesity." (PMID 34220807, 2021). "Here, we asked if exogenous IL6 could act as a protective factor against diet-induced obesity." (PMID 34465367, 2021). "This may be at least one molecular mechanism involved in the reduced B cell function in individuals with obesity, as it induces the secretion of pro-inflammatory cytokines (IL-6/TNF-α) in human peripheral blood B cells through activation of JAK2/STAT3 and p38MAPK/ERK1/2 signaling pathways." (PMID 33760825, 2021). "Additionally, another anti-inflammatory mechanism of histidine is manifested in its inhibition of the transfer of the p65 subunit of NF-kB to the nucleus, which can reduce the stimulation of IL-6 and other pro-inflammatory factors, thereby improving the inflammation of obesity." (PMID 34712134, 2021). "However, in pathological conditions such as obesity, dysfunctional adipocytes mostly produce and release pro-inflammatory adipokines such as leptin, tumour necrosis factor-α (TNFα), interleukin 6 (IL-6), interleukin 18 (IL-18), or resistin, which have atherogenic effects." (PMID 33081064, 2020). "Permeability of the BBB has previously reported to be increased in a mouse model of obesity-induced by high-fat diet, in which cognitive deficits were aggravated by excessive exposure of the brain to inflammatory cytokines, including LPS, IL-1β, IL-6, and TNFα." (PMID 32127019, 2020). "Thus, it might be possible, that HFD-induced obesity and the resulting significant increase in WAT in our model caused increased IL-6 production and subsequent secretion." (PMID 31979004, 2020). "Indeed, upon activation, JNK is translocated from the cytoplasm into the nucleus, thus promoting the expression of several pro-inflammatory genes and protein synthesis (e.g., IL-1β, TNFα, IL-8, and IL-6), impairing glucose tolerance by obesity-induced insulin resistance." (PMID 33322742, 2020).
Obesity (continued). "Obesity is well-known to increase various pro-inflammatory adipokine concentrations in serum and plasma as well as adipose tissue, whereas mRNA expression levels showed that adipocytes co-cultivated with breast cancer cells also had significantly higher IL-6, IL-1β, and TNF-α levels." (PMID 32257945, 2020). "Consequently, the accumulation of excessive macronutrients in the ATs in obesity, stimulates the release of inflammatory mediators like TNF-α and IL-6, causing the predisposition of the endothelium toward a proinflammatory state gearing to endothelial dysfunction." (PMID 32893859, 2020). "The water extract of A. camphorata ameliorates high-fat diet-induced obesity in mice by maintaining intestinal integrity, regulating intestinal microbiota to reduce fat accumulation and serum TG level and reversing inflammatory factors such as IL-1β, IL-6 and TNF-α." (PMID 32932919, 2020). "It should be noted that obesity may lead to some changes in the permeability of the blood-brain barrier, resulting in obesity-related metabolites and inflammatory factors, such as free fatty acids and IL-6, and even some immune cells, more likely to enter the central nervous system." (PMID 33299381, 2020). "During obesity, adipocytes undergo hypertrophy that leads to an increase of adipose tissue size followed by hypoxia conditions, which contribute to the secretion of proinflammatory adipokines, such as TNFα, TGFβ, IL-6, and MCP-1 by adipocytes and other cells present in adipose tissue." (PMID 33133214, 2020). "It cannot be excluded that IL6, which is an acute marker of inflammation is not a good marker for chronic low-grade inflammation which may be associated with obesity in children." (PMID 33081030, 2020). "However, it is unclear whether IL-6 involved in the senescence of BMSCs in high-fat diet (HFD)-induced obesity." (PMID 33679606, 2020). "Along with the development of antivirals and vaccines that specifically prevent or ameliorate the SARS-CoV-2 infection, several anti-obesity-related aspects could be considered as a supportive therapy, for example, anti-inflammatory cytokines like anti-IL-6 and administration of MSCs." (PMID 32806722, 2020). "Furthermore, a positive correlation trend was observed between obese adipose tissue and mRNA IL‐6 levels, which may suggest that adipose tissue is the source of IL‐6 production in the state of obesity." (PMID 32313680, 2020). "The reaction to obesity-related inflammation is the activation of the NF-ĸB transcription factor, which enhances, among others, the production of pro-inflammatory interleukins such as IL-1, IL-6 and TNF-α, and the concentration of C-reactive protein also increases." (PMID 32872598, 2020). "Moreover, obesity could induce an increase of the serum concentrations of IL-6, TNF-α, and IL-1β in obese rats." (PMID 30854010, 2019). "However, in a state of accelerated progression induced by obesity, a detriment of pro-inflammatory IL-6 and TNF-α production within the bone marrow may support the disruption of both myelopoiesis and lymphopoiesis." (PMID 31616626, 2019). "Other interrelated hypotheses appear to be justified too, specifically that vitamin D metabolism and 25(OH)D synthesis are impaired as a result of hepatic steatosis developing in obesity, and that high levels of leptin and IL-6 impair 25(OH)D synthesis by affecting VDR receptors." (PMID 30881343, 2019). "Obesity-induced skeletal muscle inflammation, characterized by increased levels of inflammatory cytokines such as tumor necrosis factor α (TNFα) and interleukin-6 (IL-6), promotes an imbalance in muscle protein synthesis and degradation leading to muscle atrophy." (PMID 31312114, 2019). "Furthermore, IL-6 plasma levels correlate with endothelial dysfunction, arterial stiffness, and the magnitude of subclinical atherosclerosis and are also predictive of incident type 2 diabetes and obesity." (PMID 30678164, 2019).
Obesity (continued). "RBP4 is thought be related to obesity, insulin resistance, type-2 diabetes, and metabolic syndrome and is suggested to be an early indicator of the development of insulin resistance and metabolic syndrome, and that this adiponectin is more sensitive to insulin than leptin, IL-6, and CRP." (PMID 30761880, 2019). "Hence, obesity-associated increases in CCL2 and CCL5 levels, together with an increase in estrogen and pro-inflammatory mediators such as leptin, IL-6, IL-1β, and TNF-α could facilitate MDSC accumulation." (PMID 31475003, 2019). "Altogether, this may suggest that higher values of T-C, LDL-C or inflammation biomarkers are mostly due to obesity, but not IL6 polymorphism, and that fat intake significantly modifies the gene effect on lipid metabolism." (PMID 31295854, 2019). "However, 4 of the 5 mice that displayed detectable serum IL-6 at this time point were in the top tertile of obesity following the diet suggesting the subset of mice displaying this parameter might be more prone to DIO." (PMID 31262998, 2019). "Furthermore, we did not demonstrate any correlation between circulating spexin and the inflammatory cytokine IL-6, which is considered the best biomarker of obesity-induced, local and systemic low-grade inflammation associated with the development of insulin resistance." (PMID 31810188, 2019). "Therefore, by activating Arid5a, IL-6 is involved in the inhibition of adipogenesis and obesity." (PMID 31867000, 2019). "Interestingly, adding IL-6 to our models examining association with vegetarian diet exposure did not alter the protective effect of the diet on obesity." (PMID 31024919, 2019). "Thus, the roles of obesity, aging and menopause in IL-6 levels need to be further explored." (PMID 31509577, 2019). "Furthermore, TNF-α and IL-6, obesity-related inflammatory cytokines, were decreased." (PMID 30258363, 2018). "Il15 ablation in mice has been reported to result in a significant increased weight gain independent of appetite; notably, the mice do not display obesity-associated inflammation, characterized as an increase of serum IL-6 and tumor necrosis factor-α concentrations." (PMID 30382157, 2018). "However, evidence against the anti-obesity role of IL-6 during HFD feeding has been reported." (PMID 30134607, 2018). "C-reactive protein (CRP), an acute-phase protein secreted by the liver in response to interleukin-6 (IL-6) and tumor necrosis factor (TNF)-α, is a well-characterized marker of inflammation, and increased circulating levels have been shown to be associated with obesity and increased metabolic risk." (PMID 29760934, 2018). "Importantly, of the investigated cytokines, only IL-6 was upregulated in colitis of obese mice implicating that IL-6 might have a role in obesity-induced CAC development." (PMID 29695802, 2018). "Thus, elevated hepatic SOCS3 levels in obesity impair both insulin and IL-6 signaling, thereby inducing a vicious cycle that might ultimately lead to cancer." (PMID 30591653, 2018). "Furthermore, serum and synovial fluid may be involved in OA progression through the regulation of pro-inflammatory markers such as IL-1β, IL-6, IP-10, and leptin in obesity conditions." (PMID 29843440, 2018). "Similarly, IL-6 mRNA expression by PBMC was reported to be decreased in obesity." (PMID 30356719, 2018). "Next, we asked whether the obesity-induced elevation in IL-6 is driving CAC development." (PMID 29695802, 2018). "Moreover, we have demonstrated previously that IL-6 exerts beneficial effects in lean mice by limiting hepatic inflammation, whereas the chronic low-grade elevation of IL-6 in obesity abrogates these functions, presumably via the development of IL-6 resistance." (PMID 29695802, 2018).
Obesity (continued). "TNFSF14/HVEM (herpesvirus entry mediator) are involved in obesity-induced inflammation by recruiting and enhancing macrophage lineage in adipose tissue, thus subsequently responsible for the release of several pro-inflammatory cytokines including TNFα, IL6 and MCP-145." (PMID 30242179, 2018). "In addition, it may be involved in OA progression in serum and synovial fluid by the regulation of pro-inflammatory markers such as IL-1β, IL-6, IP-10, and leptin in the obesity condition." (PMID 29843440, 2018). "Interestingly, other inflammatory markers, such as interleukin-15 (IL-15), tumour necrosis factor alpha (TNF-α), interferon gamma-induced protein 10 (IP-10), interleukin 6 (IL-6), and interleukin 8 (IL-8), correlated only with the microbiota profiles from children developing obesity." (PMID 30534614, 2018). "Therefore macrophages and their neighbouring Leydig cells will be exposed to any obesity related increase in serum IL-6, which may in turn impair testosterone production." (PMID 28286655, 2017). "Furthermore, both IL-6+ Th17 cells and obesity may occur in the same individuals, leading to exacerbated T2D." (PMID 28061846, 2017). "The report showed that IL-6 may be an important regulator to activate macrophages, which are an anti-inflammatory mediator and repairs tissues in inflammatory conditions such as obesity." (PMID 28654680, 2017). "Our outcomes indicate a novel function of IL-6 on the insulin metabolism expanding the possibilities for new potential therapeutic strategies, focused on insulin degradation, for the treatment and/or prevention of diseases related to hyperinsulinemia, such as obesity and T2DM." (PMID 28429777, 2017). "However, levels of IL-5, IL-6, and IL-13 went down in a dose-dependent manner and it could be interpreted that BoE supplementation could ameliorate the obesity related inflammatory features in the circulation system." (PMID 29292401, 2017). "However, the role of elevated IL-6 levels in depressed patients may need to be interpreted in a sex-specific manner as well as to include other confounding factors such as obesity." (PMID 29176954, 2017). "We found that IL-6 production was significantly increased in the L-OP, L-OR, M-OP groups, and similar results have also been described in other high-lard-induced obesity studies in mice, suggesting that IL-6 could serve as a marker of high-fat diet intake in epididymal adipose depots." (PMID 29141038, 2017). "Altered expression of immune system molecules such as interleukins IL-1, IL-6, IL-18, tumor necrosis factor alpha (TNF-α), serum amyloid A (SAA), and plasminogen activator inhibitor-1 (PAI-1), among others, has been associated with the development of chronic inflammation in obesity." (PMID 28319103, 2017). "IL-6 is a multifaceted pleiotropic cytokine, which may play a pivotal role in obesity." (PMID 27413547, 2016). "IL-6 and TNF-α, which can be elevated in obesity and insulin resistance, have been confirmed to inhibit endothelial-dependent vasodilatation, and the degenerative endothelial vasodilatation in response to IL-6 and TNF-α can result in the reduction of NO availability." (PMID 27616738, 2016). "Interleukin-6 (IL-6) can be considered an adipokine since it is released by adipocytes from obese individuals, which occurs in a size-dependent manner (i.e., larger adipocytes release greater amounts of IL-6) and links obesity to a state of low-grade inflammation." (PMID 26578976, 2015). "We hypothesize that increased maternal obesity-induced inflammation suppresses development of the DA neural circuit, as treatment with inflammatory cytokines, interleukin-6, IL-1β, and tumor necrosis factor-α, decrease the survival of DA neurons in the substantia nigra." (PMID 26150767, 2015). "The in vivo release of IL-6 by whole-body adipose tissue could contribute to 15–35% of the systemic IL-6 in human and circulating levels and adipocytes production of IL-6 are increased in obesity." (PMID 25789857, 2015).
Obesity (continued). "In contrast, the present study showed that CRP predict CVD risk independent of the Framingham Risk Score variables, and in a pathophysiological perspective, our results indicate indirectly that interleukin-6-related pathways may play a role in overweight- and obesity related CVD." (PMID 26035431, 2015). "The IL6 role in NASH is controversial since it was postulated that is a key factor in the progression of this disease and the development of IR and other researchers have assumed that IL6 may limit endotoxemia and obesity-associated IR." (PMID 25668433, 2015). "Thus, IL-6 may play an important role in the contribution of ADSCs to obesity-related cancer incidence." (PMID 25797257, 2015). "It was reported that treatment with cytokines TNF-α or IL-6 in cultured pig hepatocytes decreased apoA-IV mRNA levels, suggesting that the cytokines may contribute to dietary-induced obesity through down-regulation of the important satiety signal apoA-IV expression." (PMID 25861245, 2015). "In mouse models of obesity, macrophages switch from an anti-inflammatory M2 phenotype (producing IL-10) to a pro-inflammatory M1 phenotype, which overexpress inflammatory cytokines including IL-6 and TNF-α32 and are likely to be a major contributing source of these cytokines in adipose tissue." (PMID 25388403, 2015). "The mechanisms by which obesity increases sIgA concentrations are not known, but they are possibly associated with chronic low-grade inflammation, characterized by elevated concentrations of serum pro-inflammatory marker IL-6." (PMID 26264971, 2015). "However, no GWAS studies have found IL-6 genetic variants to be associated with obesity measures in Caucasian or African American populations." (PMID 24962479, 2014). "However, the correlation between IL-6 and obesity or insulin resistance is controversial." (PMID 24733068, 2014). "Given the anti-inflammatory and vasculoprotective actions of adiponectin and the presentation of obesity as a chronic inflammatory state, the inverse association between decreased serum adiponectin levels and increased serum levels of IL-6 in our study is not surprising." (PMID 24719717, 2014). "Obesity has been characterized as a state of chronic low‐grade inflammation, due to the increased secretion and subsequent ~2‐ to 3‐fold elevation in systemic inflammatory markers, including tumor necrosis factor‐α, interleukin‐1β (IL‐1 β), and interleukin‐6 (IL‐6)." (PMID 24997069, 2014). "Finally, we monitored IL6 mRNA levels, a proinflammatory cytokine that might play a role in obesity and metabolic syndrome." (PMID 24693420, 2014). "However, neither obesity nor activation of IL-6/STAT3 cause cancer on their own, but increase the possibility of progression to cancer of hepatocytes that have earlier acquired an oncogenic mutation." (PMID 25533006, 2014). "Furthermore, increased levels of IL-6 may be a response to impaired IL-6 signaling, which is poorly defined in many clinical studies of obesity, insulin resistance, and diabetes." (PMID 24563869, 2014). "In obesity, the intra-abdominal adipose tissue growth promotes increased pro-inflammatory cytokines infiltration and activation, such as tumor necrosis factor (TNF-α) and interleukin 6 (IL-6), which denotes the primary causes for chronic inflammation, morbidity and mortality risk." (PMID 24979131, 2014). "In obesity, increased secretion of IL-6 may contribute to metabolic dysfunction." (PMID 24741576, 2014). "We also did not observe an association between sera IL-6 levels and obesity." (PMID 24741576, 2014). "Interestingly our Ecuadorian “healthy” control group indeed had higher levels of CCL4 and IL-6, suggesting that in particular obesity and dyslipidemia determine a higher level of these classical pro-inflammatory cytokines in serum, and not (only) the diabetes state and/or pathology per se." (PMID 25500583, 2014).